MYH9 (myosin heavy chain 9)
Diseases named in the same sentence as MYH9 in open-access papers (continued):
Sharing a sentence is not in itself a finding about the gene and the disease.
glioma (continued). "Immunoprecipitation and mass spectrometry revealed MYH9 as a potential binding partner of THBS1 in glioma cells and suggested that the latter may regulate the function of the MYH9 protein." (PMID 34635636, 2021). "Elucidation of the THBS1/MYH9 axis in regard to the inhibitory effect of apitinib on glioma malignancy may provide new targets for the treatment of gliomas." (PMID 34635636, 2021). "In the present study, we revealed that HMGA1 and MYH9 were upregulated in gliomas and their expression correlated with WHO grade, and HMGA1 promoted the acquisition of malignant phenotypes and chemoresistance of glioma cells by regulating the expression of MYH9 through c-Jun-mediated transcription." (PMID 34887392, 2021). "Simultaneous THBS1 overexpression and MYH9 knockdown suppressed glioma cell invasion and migration." (PMID 34635636, 2021). "To confirm whether HMGA1 modulating of MYH9 was responsible for the promotion of the proliferation, migration, and invasion of glioma cells, we utilized an MYH9-overexpression vector in shHMGA1 glioma cells." (PMID 34887392, 2021). "Moreover, MYH9 overexpression significantly promoted glioma cell proliferation." (PMID 37770914, 2023). "Thus, our data indicated that MYH9 is a potential oncogene in glioma." (PMID 37770914, 2023). "Therefore, the actual function of MYH9 in gliomas is worth exploring." (PMID 34887392, 2021). "However, the expression and role of MYH9 in gliomas are still undetermined." (PMID 34887392, 2021). "Therefore, HMGA1 and MYH9 play essential roles in gliomas, which should be considered as tumoral enhancers with significant value as unfavorable progression indicators for patients with glioma, and may serve as feasible therapeutic targets in the future." (PMID 34887392, 2021). "Further multivariate analysis demonstrated that WHO grade, HMGA1, and MYH9 expression significantly correlated with patient survival (P = 0.01, P = 0.002, and P < 0.001, respectively), indicating that these three factors should be treated as independent prognostic factors in patients with glioma." (PMID 34887392, 2021). "However, our understanding of the role of MYH9 in gliomas is limited." (PMID 34887392, 2021). "Glioma cells were treated with different TMZ concentrations after 48 h, and the inhibition of cell viability was calculated after MYH9 knockdown." (PMID 37770914, 2023). "We found that elevated MYH9 levels were negatively correlated with the OS and progression-free survival (PFS) of patients with glioma." (PMID 37770914, 2023). "The immunofluorescence assay demonstrated that MYH9 and NAP1L1 mainly colocalized in the glioma cell cytoplasm." (PMID 37770914, 2023). "In primary glioma tissues from our department, both HMGA1 and MYH9 were upregulated in glioma samples compared to NB tissues." (PMID 34887392, 2021). "Immunofluorescent detection of MYH9 and β-catenin was performed on glioma cells overexpressing HMGA1; we observed increased cytoplasmic expression of MYH9 and total expression of β-catenin." (PMID 34887392, 2021). "Three specific constructs to knockdown MYH9 expression (KD1, KD2, and KD3) were designed and transfected into glioma cells that stably overexpressed THBS1 to determine the role of MYH9 in glioma cell migration and invasion." (PMID 34635636, 2021). "Moreover, the immunofluorescence assay revealed that MYH9 and NAP1L1 were primarily present in the cytoplasm of glioma cells." (PMID 37770914, 2023). "QPCR showed that both HMGA1 and MYH9 mRNA levels were upregulated in glioma tissues compared to normal brain tissues (NB), and overexpressed levels of HMGA1 and MYH9 in glioma patients were positively correlated with pathological classification (WHO 2 vs. WHO 3 vs. WHO 4) (P < 0.05)." (PMID 34887392, 2021). "Moreover, MYH9 binds to GSK-3β and promotes its ubiquitinated degradation, resulting in the promotion of malignant phenotypes and chemotherapy-resistant of glioma cells." (PMID 34887392, 2021).
glioma (continued). "MYH9 knockdown inhibited glioma cell migration and invasion, even when THBS1 was overexpressed, indicating that the effect of apatinib on glioma cells likely involves the THBS1/MYH9 axis." (PMID 34635636, 2021). "Additionally, we found that MYH9 upregulation was strongly related to patient survival and is therefore a negative factor for patients with glioma." (PMID 37770914, 2023). "In addition, these data may propose new research directions regarding targeted glioma therapeutic drug development against THBS1 and the THBS1/MYH9 axis." (PMID 34635636, 2021). "Moreover, MYH9 interacted with GSK-3β to inhibit the expression of GSK-3β protein by promoting its ubiquitination; the downregulation of GSK-3β subsequently promoted the nuclear translocation of β-catenin, enhancing growth, invasion, migration, and temozolomide resistance in glioma cells." (PMID 34887392, 2021). "On the other hand, mTORC2 were not strongly interacting with GSN, MYH9, as well as AKT, a known mTORC2 substrate, in low-grade glioma cell lines." (PMID 37120454, 2023).
nephritis (15 papers, 2013 to 2025). Inflammation of renal tissue. "In the mitochondria, APE2 localizes with Myosin Heavy Chain-9 (MYH9) which is associated with nephritis." (PMID 36755963, 2023). "The genetic variants were not fully penetrant for the renal phenotype, but a subset of the patients carrying MYH9 variants suffered from nephritis, including display of foot process effacement, loss of SDs, proteinuria, and renal failure." (PMID 35265622, 2022). "Screening for nephritis and cataract, known to be associated with MYH9-RPD, by using abdominal ultrasonography, urine analysis, and ophthalmologic exam was negative." (PMID 32950057, 2020). "MYH9 gene mutations result in nephritis to varying degrees in Epstein and Fechtner syndromes." (PMID 31534799, 2019).
end-stage renal disease (13 papers, 2010 to 2026). "Both cases were diagnosed as the MYH9 disorders Fechtner syndrome before end-stage renal failure on the basis of the observation of peripheral blood smear." (PMID 31885961, 2019). "This differs from kidney involvement in MYH9-RD, which, when occurs, tends to evolve progressively into end-stage renal failure." (PMID 22558294, 2012).
viral infection (12 papers, 2016 to 2025). "To this end, we quantified MYH9 mRNA and endogenous protein expression in A549 cells after viral infection." (PMID 41217108, 2025). "To analyze Myh9 activity in viral infection, we isolated bone marrow-derived macrophages (BMDMs) from 8- to 12-week-old C57BL/6 mice, and we transfected a mouse-specific siRNA (simMYH9) in fully differentiated BMDMs for 48 h." (PMID 41217108, 2025). "We also found that viral infection upregulates MYH9 endogenous expression, suggesting a virus-driven positive regulatory mechanism." (PMID 41217108, 2025). "Western blot analysis showed that MYH9 levels were significantly increased at 24 hpi, suggesting that virus infection establishes a positive feedback-like mechanism to further increase infection levels." (PMID 41217108, 2025). "To get further insight into the proviral activity of MYH9, we sought to analyze the effect in viral infection of decreasing the motor/contractile activity of NM-IIA or preventing its self-assembly into bipolar filaments." (PMID 41217108, 2025). "In contrast, overexpression of MYH9 or PRA enhanced viral infection in wild-type A549 and H1299 cells." (PMID 37645223, 2023). "Nonetheless, it has been indicated that membranous expression of MYH9 facilitates viral infections, by acting as a receptor for sialylated RNA viruses." (PMID 34425650, 2021). "The role of MYH9 as a potential receptor or co-receptor for viral infection, as well as mechanisms of interaction between viral proteins and MYH9, are poorly understood." (PMID 31649651, 2019). "More recently, MYH9 has also been demonstrated to act as a negative regulator during early viral infection, whereby it recognizes sialic acids on sialylated RNA viruses then suppresses pro-inflammatory signaling via the DAP12-Syk pathway." (PMID 31649651, 2019). "Thus, MYH9 is a broad proviral host factor whose expression is positively modulated to increase viral infection levels by a mechanism currently under investigation." (PMID 41217108, 2025). "We next asked whether viral infection could upmodulate the expression levels of MYH9 to further support infection." (PMID 41217108, 2025). "Thus, to analyze the role of MYH9 in viral infection, we did short-interfering RNA (siRNA)-mediated knockdowns in human and mouse cells, which transiently reduced MYH9 mRNA and protein expression, without compromising cell viability 48 h post-transfection." (PMID 41217108, 2025). "Here, we examined whether the Jak, Syk, and/or Src families of NRTKs may phosphorylate MYH9 upon virus infection." (PMID 41217108, 2025). "By analyzing different families of non-receptor tyrosine kinases (NRTKs), we identified that members of the Src family kinase would phosphorylate MYH9 upon viral infection, which could be therapeutically exploited." (PMID 41217108, 2025). "Since Src kinases phosphorylate hundreds of proteins to modulate their function in several physiological and pathological processes, we coupled MYH9 knockdown with PP1 treatment to analyze whether these kinases may be activating MYH9 upon virus infection." (PMID 41217108, 2025). "Hence, preventing the assembly of NM-IIA in bipolar filaments, which is essential for the motor/contractile activity of MYH9, also reduces viral infection." (PMID 41217108, 2025). "Upon demonstrating that viral invasion triggers tyrosine phosphorylation of MYH9, we examined whether phosphorylation of Y277 and/or Y1805 might regulate its function in virus infection." (PMID 41217108, 2025). "Here, we investigated whether MYH9 enhances viral infection and how its activity would be regulated during this process." (PMID 41217108, 2025). "Thus, to determine the molecular basis of the activity of MYH9 in viral infection, we first used the inhibitor blebbistatin, which binds to MYH9 ATPase site, hence suppressing the overall mechanical activity of NM-IIA." (PMID 41217108, 2025).
viral infection (continued). "Furthermore, we showed that virus infection drives the accumulation of MYH9 at the plasma membrane to support post-binding steps of virus entry and that phosphorylation of the tyrosine residues 277 and 1805 is critical for its function in infection." (PMID 41217108, 2025). "Here, we analyzed whether MYH9 would enhance viral infection, as it does phagocytic engulfment, and how its activity in infection is regulated." (PMID 41217108, 2025). "However, the roles played by MYH9 during viral infection or infections involving other pathogens have only been recently investigated." (PMID 31649651, 2019). "A recent report demonstrates that MYH9 plays a key role in some virus infections." (PMID 27686528, 2016). "By determining that virus infection triggers the phosphorylation of MYH9 in two tyrosine residues essential for its proviral activity, and the family of non-receptor tyrosine kinases involved in this process, we may also provide new cellular targets to develop antiviral therapies." (PMID 41217108, 2025). "Furthermore, we demonstrated that MYH9 is actively translocated to the plasma membrane upon viral infection to support post-binding steps of entry, and that phosphorylation of two key tyrosine residues in its head and tail domains is essential for its function in viral infection." (PMID 41217108, 2025). "MYH9 can act as a coreceptor for SARS-CoV-2 to enter the host and enhance viral infection by promoting the endocytosis of SARS-CoV-2 dependent on ACE2, but this process does not require the participation of TMPRSS2 and the CatB/L pathway." (PMID 37645223, 2023). "Non-muscle myosin heavy chain 9 (MYH9), identified as a cell receptor for PRRSV, interacts with CD163 to promote virus infection." (PMID 36187992, 2022). "Collectively, these findings support the conclusion that MYH9 filament aggregation is required for PRRSV internalization and subsequent viral infection." (PMID 31649651, 2019). "Equally importantly, overexpression of MYH9 did not enhance SARS-CoV-2 pseudoviral infection in ACE2 knockout A549 cells but only enhanced viral infection in wild-type A549 cells." (PMID 37645223, 2023). "In addition, immunofluorescent staining revealed that MYH9 and SARS-CoV-2 S colocalized mainly to the cell membrane during transfection and authentic viral infection." (PMID 34873039, 2021). "Indeed, we found that MYH9 does not enhance SARS-CoV-2 pseudovirus infection in ACE2-depleted A549 cells but rather increases viral infection in WT A549 cells." (PMID 34873039, 2021). "Moreover, interactions between MYH9 and viral proteins such as PRRSV-GP5 or gB of HSV-1 have been observed, with blockage of MYH9 binding with specific antibody resulting in inhibition of virus infection in those systems." (PMID 31905776, 2019).
diabetic kidney disease (11 papers, 2011 to 2023). Progressive kidney disorder caused by vascular damage to the glomerular capillaries, in patients with diabetes mellitus. "MYH9 polymorphisms have been described to be associated with the risk of CKD in non-diabetic nephropathy, HIV nephropathy and FSGS." (PMID 24658608, 2014). "Coding variants in APOL1 are major susceptibility loci for non-diabetic nephropathy; however, independent, weaker MYH9 effects remain plausible." (PMID 21698141, 2011). "However, polymorphisms in MYH9 have been proven to be associated with diabetic nephropathy in 1963 European Americans, including 536 cases with T2DM-ESRD and 1427 nonnephropathy controls." (PMID 29862302, 2018). "This study provides evidence that MYH9 downregulation in diabetic nephropathy induces podocyte dysfunction through the reorganization of the actin cytoskeleton, which is driven by TRPC6-mediated Ca2+ influx by NOX4-mediated ROS generation." (PMID 31118506, 2019). "In diabetic nephropathy, many putative pathways might contribute to the downregulation of MYH9 expression." (PMID 31118506, 2019). "Indeed, multiple MYH9 SNPs have been identified as powerful predictors of non-diabetic kidney disease in African Americans, Hispanic-Americans, and individuals of European ancestry." (PMID 30340464, 2018). "Although FERM-domain containing proteins interact with myosins, we do not feel that our genetic results support FRMD3 and MYH9 variants directly interacting to initiate diabetic nephropathy in African Americans." (PMID 21698141, 2011). "Our findings implicate MYH9 as an important component in the maintenance of the biological function of podocytes and suggest pathways that might be affected by MYH9 function in the pathogenesis of diabetic nephropathy." (PMID 31118506, 2019). "MYH9 may be a potential target for treating diabetic nephropathy." (PMID 31118506, 2019). "Therefore, we tested for interactions between single nucleotide polymorphisms across the genome with APOL1 and MYH9 non-diabetic nephropathy risk variants in African Americans with presumed diabetic nephropathy." (PMID 21698141, 2011). "Overall, these data implicate both MYH9 and APOL1 as significant biological contributors to non-diabetic nephropathy and intimate context-dependent roles in disease pathology." (PMID 26147622, 2015).
esophageal squamous cell carcinoma (11 papers, 2016 to 2025). Esophageal squamous cell carcinoma (ESCC) is a type of esophageal carcinoma (EC) that can affect any part of the esophagus, but is usually located in the upper or middle third. "Another study disclosed that membranous and cytoplasmic expression of MYH9 in esophageal squamous cell carcinoma was definitely associated with lymph node metastasis, serosal invasion, and stage of the disease." (PMID 34425650, 2021). "In contrast, recent reports indicate that MYH9 functions as an oncogene in gastric, colorectal non-small cell lung, nasopharyngeal carcinoma, and esophageal squamous cell cancers 40-44." (PMID 39440063, 2024). "Sterile alpha motif domain-containing protein 9 (SAMD9) promotes EMT and metastasis of esophageal squamous cell carcinoma by stimulating MYH9-mediated GSK3β/β-catenin signalling." (PMID 37875476, 2023). "Non-muscle myosin heavy chain 9 (MYH9) is one novel low frequency mutated gene identified in esophageal squamous cell carcinoma (ESCC) using next-generation sequencing." (PMID 32788880, 2020). "In esophageal squamous cell carcinoma, PTP1B promotes cell invasion and migration by dephosphorylating MYH9 at Y1408, which results in increased EGFR expression." (PMID 34606417, 2021).
nasopharyngeal carcinoma (11 papers, 2020 to 2025). A carcinoma arising from the nasopharyngeal epithelium. "For example, in nasopharyngeal carcinoma, DNAJA4 directly interacts with MYH9, recruiting PSMD2 to promote MYH9 ubiquitination and degradation, thereby inhibiting nasopharyngeal carcinoma migration and EMT." (PMID 39988672, 2025). "NMHC-IIA (MYH9) was described as another EBV receptor in nasopharyngeal carcinoma, which interacts with gH/gL of the EBV envelope." (PMID 39766110, 2024). "In our series of clinical specimen verification and in vitro cell experiments, MYH10 has been confirmed to play a consistent role with MYH9 as a tumor suppressor gene in nasopharyngeal carcinoma." (PMID 32226520, 2020). "Moreover, it has been shown that DNAJA4 inhibits invasion and metastasis of nasopharyngeal carcinoma through PSMD2-mediated proteasomal degradation of MYH9." (PMID 39550407, 2024). "We hypothesized that the inhibitory effect of MYH10 in nasopharyngeal carcinoma was related to the co-polymerization of NMIIA (MYH9) and NMIIB (MYH10) 23-24." (PMID 32226520, 2020). "in 2020 identified that the 3′-UTR shortening of fibronectin type III domain containing 3B (FNDC3B) mRNA mediated its overexpression in Nasopharyngeal carcinoma(NPC)and promoted NPC progression by targeting myosin heavy chain 9 (MYH9)." (PMID 36816917, 2023). "However, some reversed studies showed that MYH9 functions as a potential oncogene in most tumors and promotes the tumor occurrence, metastasis and tumor stemness formation 16-19, including esophageal squamous cell carcinoma and nasopharyngeal carcinoma 20,21." (PMID 35414777, 2022). "Additionally, it disrupts the interaction with its binding partner MYH9, effectively inducing FOXO1-mediated cisplatin sensitivity in nasopharyngeal carcinoma." (PMID 39149512, 2024).
pancreatic cancer (11 papers, 2021 to 2025). "Combined with previous in vitro results, we suggest that GALNT5 confers chemotherapy resistance to FOLFIRINOX in pancreatic cancer cells by binding to MYH9 and inhibiting NOTCH signaling in vivo." (PMID 39433745, 2024). "Our data suggest that the 4H12 mAb can serve as a tool for investigating the role of MYH9 pancreatic cancer biology and prognosis." (PMID 34425650, 2021). "This antibody can be used as a tool to study the role of MYH9 in the biology of pancreatic cancer." (PMID 34425650, 2021). "Moreover, MYH9 modulates EMT mediated by β-catenin to facilitate the proliferation, migration and invasion of pancreatic cancer (PC) cells." (PMID 33959503, 2021). "Therefore, the surface and intracellular expression of MYH9 in PACC and PDAC should be further evaluated in a larger sample size, and the correlation of either surface or cytoplasmic expression with pancreatic cancer outcome should be determined." (PMID 34425650, 2021).